IGF1 (insulin like growth factor 1)
Diseases named in the same sentence as IGF1 in open-access papers (continued):
Sharing a sentence is not in itself a finding about the gene and the disease.
Insulin resistance (continued). "The pathophysiological mechanisms of insulin resistance are possibly secondary to a relative prolonged nutritional deficiency in the fetus, during which time the fetal metabolism constantly readjusts to slow growth with relative resistance to insulin, IGF-1, and GH." (PMID 21771322, 2011). "High blood insulin levels, resulting from insulin resistance, stimulate the release of insulin-like growth factor-1 (IGF-1), promoting cell growth and division in the body, including in the liver." (PMID 41607999, 2026). "The results suggested that the IGF-1 signaling pathway can be involved in the pathogenesis of psoriasis and its comorbidities, especially metabolic disorders such as insulin resistance, diabetes, and metabolic syndrome." (PMID 41635444, 2026). "Portal shunting and insulin resistance can significantly lower IGF-1 levels, decrease osteoblast activity, and increase bone resorption, thereby disrupting bone balance." (PMID 41601928, 2026). "Diet-related metabolic disorders are multilayered, but common features include peripheral insulin resistance, compensatory overproduction of insulin, and increased bioavailability of insulin-like growth factor-1 (IGF-1)." (PMID 41484057, 2026). "Rising adiposity and IGF-1 together explained 34% of the variance in insulin resistance in boys and 35% in girls over the 3 years preceding pubertal onset." (PMID 39611962, 2025). "Other theories suggest that insulin resistance and increased insulin-like growth factor-1 (IGF-1) promote cell proliferation and higher free estrogen levels through a reduction in sex-hormone-binding globulin." (PMID 40862803, 2025). "The two main proposed mechanisms involve an indirect effect through modulation of insulin resistance—by reducing insulin IGF1 (Insulin like Growth Factor) signaling and controlling hyperglycemia—as well as a direct effect on cell cycling and apoptosis." (PMID 41156128, 2025). "IGFBP-3 is the primary carrier protein for IGF-1 and exerts deleterious effects on insulin resistance and adipose tissue function by promoting the production of pro-inflammatory cytokines in adipocytes." (PMID 41226444, 2025). "Higher secretion of insulin and IGF-1 due to insulin resistance also increases the production of reactive oxygen species." (PMID 40572713, 2025). "Obesity-induced insulin resistance results in chronic hyperinsulinemia that activates the insulin-like growth factor-1 (IGF-1) signaling pathway, stimulating PI3K/AKT and MAPK pathways independently of estrogen." (PMID 41514656, 2025). "Insulin resistance and compensatory hyperinsulinemia stimulate proliferative pathways via the IGF-1 and insulin receptors, promoting cellular growth and inhibiting apoptosis in thyroid follicular cells." (PMID 40731899, 2025). "The endocrine response diminishes due to insulin resistance, lower levels of insulin-like growth factor-1 (IGF-1), and reduced growth hormone levels." (PMID 41464873, 2025). "Biological mechanisms implicate chronic insulin resistance and hyperinsulinemia as key mediators of oncogenesis, partly through activation of insulin/IGF-1 signaling pathways and metabolic reprogramming." (PMID 40995175, 2025). "Due to IGF-1-independent action, IGFBP-3 has been associated with impaired glucose tolerance and insulin resistance in mouse models and in vitro studies as well." (PMID 41226444, 2025). "It has been reported that IGF-1 improved neuronal complexity and synaptic connectivity under insulin resistance conditions." (PMID 40283962, 2025). "By the onset of puberty, there is a surge in GH and IGF-1, which increases insulin resistance, resulting in increased LP oxidation and increased FFA in the circulation." (PMID 40019178, 2025). "This contributes to a state of chronic low-grade systemic inflammation and insulin resistance, leading to elevated circulating levels of insulin and insulin-like growth factor-1 (IGF-1)." (PMID 40647462, 2025).
Insulin resistance (continued). "Insulin resistance and IGF‐1 signaling are also mechanisms by which obesity affects cancer progression since hyperinsulinemia leads to increased IGF‐1, enhancing tumor cell proliferation and metastasis." (PMID 40387523, 2025). "Insulin resistance leads to increased insulin-like growth factor 1 (IGF-1), which activates cancer-promoting pathways like AKT/mTOR/PI3K and ERK/RAS/MAPK, supporting tumor growth and survival." (PMID 40507982, 2025). "Conversely, in insulin resistance, including obesity and aging, increased insulin and IGF-1 signaling together promote inflammation." (PMID 41514592, 2025). "Insulin resistance and decreased insulin or IGF-1 levels affect Akt phosphorylation and phosphorylated GSK3β levels, which promote the breakdown of β-catenin." (PMID 40725728, 2025). "The significantly lower serum IGF‐1 levels in diabetic patients suggest a potential link between insulin resistance and impaired IGF‐1 production." (PMID 41199981, 2025). "Metabolic dysregulation, including insulin resistance and hyperinsulinemia, creates a pro-tumorigenic environment by increasing free insulin-like growth factor 1 (IGF-1) levels and enhancing hormone availability, which supports hormone-dependent cancers." (PMID 40282431, 2025). "Insulin resistance and impaired growth hormone function, common in HCV‐infected patients, are associated with reduced IGF‐1 levels." (PMID 40060195, 2025). "Men with diabetes also exhibit insulin resistance, which leads to an elevation in the serum levels of insulin and insulin-like growth factor-1 (IGF-1), promoting cell proliferation and survival in various cancers, including prostate cancer." (PMID 41367482, 2025). "Diabetes and obesity synergistically exacerbate insulin resistance, chronic inflammation, and hormonal imbalances, increase IGF-1, free estrogen, and other pro-cancerous biomarkers, and cause immune dysregulation." (PMID 41440200, 2025). "They suppress protein synthesis by inhibiting the mTOR pathway and reducing IGF-1 signaling, as well as inducing insulin resistance and IGF-1 resistance." (PMID 40648864, 2025). "These phenotypes are well established in HFD-fed mice, and insulin resistance is known to impact brain function and behavior through pathways overlapping with IGF-1." (PMID 41155299, 2025). "Diabetic patients had significantly lower IGF‐1 levels, likely due to insulin resistance impairing IGF‐1 production." (PMID 41199981, 2025). "In an analysis of pre- and post-treatment (surgical) acromegaly patients, decreased levels of GH, IGF-1, and insulin resistance were detected, while visceral and subcutaneous fat mass increased." (PMID 40725515, 2025). "Molecular findings suggest that insulin resistance and dysregulated IGF-1 signaling promote atherosclerosis and a pro-inflammatory state." (PMID 40283962, 2025). "It has been confirmed that the potential mechanisms behind this relationship involve insulin resistance, inflammation, and stimulation of the insulin-like growth factor 1 (IGF-1) pathway, thereby promoting tumor growth." (PMID 40823011, 2025). "Experimental work should explore how TyG-related insulin resistance promotes colorectal tumorigenesis through insulin/IGF-1 signaling, PI3K–AKT–mTOR activation, chronic inflammation, and microbiome or bile acid alterations." (PMID 41479778, 2025). "In the postpartum period, the uncoupling of the somatotropic axis and insulin resistance leads to a reduction in IGF-1 levels and intensifies lipolysis." (PMID 41472162, 2025). "Hyperinsulinemia and insulin resistance increase mitogenic IGF-1 signaling, while dysregulated adipokines, particularly elevated leptin and reduced adiponectin, promote cellular proliferation and impair tumor suppression." (PMID 40722646, 2025).
Insulin resistance (continued). "High adiposity raises aromatase activity and systemic estrogens, and obesity-induced insulin resistance elevates IGF-1 and adrenal androgens, which support ectopic cell survival while perturbing the hypothalamic–pituitary–ovarian axis." (PMID 40565786, 2025). "Metabolic conditions such as obesity, diabetes, and insulin resistance, combined with hormonal imbalances, can disrupt the body’s natural growth regulation systems, including the insulin-like growth factor-1 (IGF1) pathway." (PMID 39796756, 2025). "In the early phase of insulin resistance, increased IGF-1 levels coincide with augmented insulin synthesis, leading to compensatory hyperinsulinemia." (PMID 41514592, 2025). "In MASLD, chronic insulin resistance, hyperinsulinemia, and elevated IGF-1 signaling promote epithelial proliferation and inhibit apoptosis, contributing to carcinogenesis in both the esophagus and stomach." (PMID 41228210, 2025). "VEGF, a potent proangiogenic cytokine, is markedly upregulated in diabetic retinas and correlates with insulin resistance and elevated insulin-like growth factor-1 (IGF-1) levels." (PMID 40807437, 2025). ",21 (ii) Insulin resistance, which can suppress the insulin/IGF-1 signalling pathway, inhibit protein anabolism, and/or promote protein degradation, relates to the impairment of muscle strength." (PMID 40354753, 2025). "This is consistent with the product of IGFALS (acid-labile subunit) increasing the serum half-life of IGF-1, and patients with IGFALS deficiency present with IGF-1 deficiency and insulin resistance." (PMID 40065360, 2025). "Inflammation also causes insulin resistance, and it is shown that TNF-α stimulates phosphorylation of IRS-1ser307, leading to suppression of insulin/IGF-1 signaling." (PMID 38811433, 2025). "In states of insulin resistance, IGF-1 can regulate glucose metabolism, complementing the effects of Ins, and people with diabetes can respond to IGF-1 with a beneficial effect on glucose homeostasis." (PMID 40277891, 2025). "In obese Zucker rats, elevated IGF1 coincides with insulin resistance, and in type 2 diabetic humans, the effects of IGF1 on free fatty acid (FFA) and glucose metabolism are diminished." (PMID 40105689, 2025). "As demonstrated in previous studies, reduced IGF-1 levels are independently associated with multiple cardiovascular risk factors, including NAFLD, insulin resistance, dyslipidemia (particularly low HDL-C) and metabolic syndrome." (PMID 40379763, 2025). "Some studies have shown that insulin resistance increases the risk of OP and fractures by affecting the bone turnover process; A randomized controlled trial suggests that insulin resistance may inhibit muscle-dependent bone gain by impairing the IGF-1 signaling pathway." (PMID 40235664, 2025). "Insulin resistance exacerbates muscle degradation via dysregulation of insulin and insulin-like growth factor 1 signaling." (PMID 40717956, 2025). "Concurrently, insulin resistance impairs the anabolic effects of insulin-like growth factor 1 (IGF-1) on bone remodeling, supporting the observed inverse relationship between BMI and BMD." (PMID 40702394, 2025). "Acquired GH resistance consequently causes a decrease in insulin-like growth factor-1 (IGF-1) and a compensatory increase in GH, exacerbating insulin resistance secondarily." (PMID 39457712, 2024). "Since insulin activates the PI3K/Akt/ mTOR pathway analogously to IGF-1, insulin resistance plays an important role in inhibiting the activation of the Akt/ mTOR protein synthesis signaling pathway in muscle atrophy." (PMID 38397848, 2024). "IGF-1 resistance is another mechanism involved in developing insulin resistance in peripheral tissues." (PMID 38255314, 2024). "Factors such as obesity, insulin resistance, delayed gonadal development, chronic inflammation, low-calorie intake, and use of estrogens (such as oral contraceptives) can lead to varying serum IGF1 levels." (PMID 39415786, 2024).
Insulin resistance (continued). "Hyperinsulinemia and hyperglycemia, often exacerbated by T2DM, induce insulin resistance and elevate IGF-1 levels, further activating the PI3K/AKT pathway and supporting tumor cell proliferation." (PMID 39290325, 2024). "Insulin resistance leads to increased serum levels of insulin-like growth factor 1 (IGF-1) and enhances the biological activity of IGF-1." (PMID 38977823, 2024). "The pathogenesis involves obesity-induced insulin resistance, compensatory hyperinsulinemia, and changes in sex hormones and insulin-like growth factor-1 (IGF-1) bioavailability, alongside elevated inflammation and oxidative stress." (PMID 39458471, 2024). "Insulin resistance leads to elevated insulin levels, resulting in increased secretion of insulin-like growth factor-1 (IGF-1), decreased production of sex hormone-binding globulin (SHBG), and increased levels of free sex hormones." (PMID 39469573, 2024). "Even the excess of adipose tissue seems to promote cancer cell growth and metastasis through a condition of insulin resistance and altered secretion of IGF-1, which have a direct stimulating action on thyrocyte growth." (PMID 39335476, 2024). "In the liver, GH is the major stimulator of IGF-1, and the downstream effects of IGF-1 include reducing visceral fat, lipogenesis, triglyceride accumulation, and improving insulin resistance to inhibit the development of MASLD." (PMID 40988882, 2024). "Talking about insulin resistance, high glycemic load diets encourage the development of acne vulgaris via elevating insulin-like growth factor 1 (IGF-1) levels." (PMID 38384651, 2024). "IGF-1 has been successfully employed in the treatment of certain rare lipodystrophic forms of Type 2 Diabetes in individuals with severe insulin resistance." (PMID 39578883, 2024). "The results also suggested that AC supplementation during early life can alleviate insulin resistance, IGF-1 signaling, and Wnt/β-catenin signaling." (PMID 39125288, 2024). "Meanwhile, high levels of TNF-α and IL-6 mediate insulin resistance and up-regulate insulin-like growth factor 1 (IGF-1) levels." (PMID 38481820, 2024). "Insulin resistance and hyperglycemia contribute to the upregulation of insulin and insulin-like growth factor 1 (IGF-1), which stimulate hepatocyte proliferation and inhibit apoptosis through activation of the PI3K and MAPK signaling pathways." (PMID 39610917, 2024). "Insulin resistance stimulates the hepatic synthesis of insulin-growth factor 1 (IGF-1) and increases its bioactivity by reducing insulin-growth factor binding protein 1 (IGFBP-1) and 2 (IGFBP-2) levels." (PMID 39199391, 2024). "Reduced skeletal muscle mass also contributes to insulin resistance, increases lipolysis, the release of free fatty acids from adipose tissue, and inhibits the growth hormone (GH)-insulin like growth factor 1 (IGF1) axis." (PMID 38709150, 2024). "Patients with poorly controlled T2DM exhibit higher IGF-1 levels, while those with obesity and high insulin resistance demonstrate lower IGF-1 levels." (PMID 39578883, 2024). "Relevant studies have shown that IGF-1 not only reduces both serum insulin levels and normal blood glucose levels but also improves insulin resistance in patients with T2DM and worse severe insulin resistance." (PMID 38463527, 2024). "Excess weight is often comorbid with elevated insulin and insulin resistance, blood glucose, cholesterol, sex hormones, and IGF-1." (PMID 38446316, 2024). "Previous studies have identified that the mechanisms underlying the protective effects of DR are mainly associated with a reduction in oxidative stress, glucose levels, insulin resistance, insulin-like growth factor 1 (IGF-1), and growth hormone (GH) levels." (PMID 38507875, 2024). "Further prospective studies are warranted to evaluate the potential of using IGF-1 to reduce insulin resistance and improve metabolic and glycaemic measures in individuals with T2DM and obesity or insulin resistance." (PMID 39578883, 2024).
Insulin resistance (continued). "Insulin resistance contributes to hyperinsulinemia, which enhances tumorigenesis by activating insulin-like growth factor 1 (IGF-1) signaling, a pathway that promotes cell proliferation and inhibits apoptosis." (PMID 39736510, 2024). "Accordingly, studies on IR and CRC risk used the homeostasis model of insulin resistance (HOMA-IR), circulating C-peptide, or insulin-like growth factor 1 (IGF1-) as measures of IR and insulin production." (PMID 39103728, 2024). "In the pathophysiology of obesity and cancer, hyperinsulinemia related to insulin resistance increases the bioavailability of insulin-like growth factor (IGF)-1." (PMID 37347429, 2024). "Dietary patterns with substantial increases in dietary fiber and substantial reductions in saturated fat and/or animal protein have been tested in various human trials and found to modulate serum cholesterol, insulin resistance, sex hormones, and IGF-1." (PMID 38446316, 2024). "The occurrence of cancer in these patients is mainly explained by the presence of insulin resistance and the influence of insulin-like growth factor 1 (IGF-1), with additional factors such as free fatty acids, aromatase, and adipokines." (PMID 39338262, 2024). "Our findings also align with the observation of lower mean IGF-1 levels in individuals with high Homeostatic Model Assessment for Insulin Resistance (HOMA-IR), suggesting a role for IGF-1 in insulin resistance in patients with Type 2 Diabetes Mellitus." (PMID 39578883, 2024). "The aim of this study was to investigate the correlation between serum SHBG, IGF-1 and cortisol with indices of glucolipid metabolism and insulin resistance in patients with GDM and their impact on the development of GDM." (PMID 39876919, 2024). "The level of IGF-1 is regulated by many factors (insulin resistance, insulin levels, lipids, vitamin D3, hormones, metabolic syndrome, and inflammatory parameters)." (PMID 38540997, 2024). "While insulin and IGF signaling are known for their broad impacts on metabolism and growth, genetic manipulation studies in insulin/IGF1 signaling shows that they cause insulin resistance and hyperglycemia, while extending longevity." (PMID 39161341, 2024). "Insulin resistance and subsequent hyperinsulinemia contribute to elevated levels of insulin-like growth factor 1 (IGF-1), which, in turns, promotes cell survival, stimulates cell proliferation, and facilitates angiogenesis." (PMID 39200802, 2024). "Insulin resistance, commonly observed in older adults, can impact IGF-1 signaling and contribute to anabolic resistance." (PMID 37764858, 2023). "Sleep disorders promote insulin resistance, also disrupting other hormonal pathways, particularly GH/IGF-1 and GLP-1 axis." (PMID 37445790, 2023). "Some of the known risk factors for EC include polycystic ovary syndrome (PCOS), diabetes, obesity, inflammation, insulin resistance, high estrogen concentrations, and possibly, high circulating insulin-like growth factor 1 (IGF-1) levels." (PMID 37988160, 2023). "PCOS patients generally have insulin resistance, and IGF1 can enhance pancreatic β cell viability and inhibit apoptosis by activating the Sirt1/PI3K/Akt/FoxO1 pathway, inducing insulin secretion, and alleviating oxidative damage." (PMID 37701184, 2023). "Separately, another study determined that mice with liver-specific deletion of Igf-1 show GH-induced insulin resistance contributed by excess p85α produced in the skeletal muscle." (PMID 37628845, 2023). "The association between IGF‐1, IGF‐binding protein level, and insulin resistance has been showed in several researches." (PMID 37143466, 2023). "Other studies have reported that IGF-1, myostatin, and insulin resistance were correlated with sarcopenia in elderly patients (both males and females) undergoing hemodialysis." (PMID 37764858, 2023). "Insulin resistance induces compensatory hyperinsulinaemia which increases production of insulin-like growth factor 1 (IGF-1)." (PMID 37470858, 2023).